ZNF217 (zinc finger protein 217)
Diseases named in the same sentence as ZNF217 in open-access papers (continued):
Sharing a sentence is not in itself a finding about the gene and the disease.
tumor (continued). "Although CoREST1 has been identified in complexes with factors that promote tumor progression, such as LSD1, ZNF217, ZNF198, HDAC1/2 and SIRT1, the role of CoREST1 in tumorigenesis is unclear." (PMID 25793264, 2015). "Additionally, we observed that most high-expressed m6A regulatory factors in tumor tissues had CNV gains, such as VIRMA, ZNF217, and YTHDF1." (PMID 39020010, 2024). "For instance, CIZ1, ZNF217, ZNF281, ZKSCAN3, ZNF692, ZNF750, and ZFP36 proteins are closely related to the tumor volume, lymph node metastasis status, and TNM stage, and their expression levels had statistically significant effects on the survival time of patients with colon adenocarcinoma." (PMID 36358661, 2022). "Given the large proportion of TBX2 binding sites occupied by ZNF217 in MCF7 ChIP-seq, we determined which of these regions represented TBX2-CoREST-repressed genes that may function as tumour suppressors." (PMID 35687133, 2022). "Among the tumor-related genes, the top amplified genes included ERBB2 (17q21), MYC (8q24), GNAS (20q13), EGFR (7p11), ZNF217 (20q13), CCNE1(19q12), NCOA3 (20q13), and CDK6 (7q21), and the most frequently deleted genes were CDKN2A (9p21), CDKN2B (9p21), KIT (4q12), SMAD4 (18q21), and FGFR1 (8p12)." (PMID 31541076, 2019). "Of utmost interest is that the predictive value of ZNF217 expression levels seems to reside in the initial tumor and is not the reflection of transcriptional changes following ET in the treated tumors." (PMID 30740056, 2018). "The ZNF217 low and high expression level groups were comparable in terms of Ki-67 values in the initial tumor (pre-treatment) (P = 0.20, data not shown)." (PMID 30740056, 2018). "Increased of ZNF217 expression led to decreased FPN concentration, coupled with resultant intracellular iron retention, increased iron-related cellular activities and enhanced tumor cell growth." (PMID 27768596, 2016). "In addition, we also found that high ZNF217 expression was positively correlated with higher PSA levels, higher Gleason score, advanced tumor stage, lymph node metastasis and biochemical recurrence (P<0.05)." (PMID 27768596, 2016). "Multivariate analysis demonstrated that ZNF217 over expression was independent of tumor stage, with other clinical variables having no significant impact on the model, including location." (PMID 27363029, 2016). "ZNF217 RNA levels were also higher in Japanese tumor samples than in non-Japanese samples (P = 0.027)." (PMID 25658832, 2015). "Several genes located on 20q, for example, the oncogenes located on 20q13.1, such as CAS/CSE1L, NABC1, ZNF217, Aurora2 (BTAK, STK15) and the ubiquitin-conjugating enzyme E2C (UBE2C), have been described to have an important role in tumour progression and liver metastases." (PMID 21673680, 2011). "Moreover, the chromosome 20q13.2 region, which includes ZNF217 (focal level), tended to be amplified specifically in Japanese tumor samples, but not in the Korean or German samples; this findings was confirmed by Q-PCR." (PMID 25658832, 2015). "Moreover, ZNF217 was a better predictor of survival than ERα status but not tumor size by multivariate analysis." (PMID 24962896, 2014). "In conclusion, a complex and close interplay exists between ZNF217 and specific ncRNA regulatory axes where ZNF217 can act either as a downstream effector of oncogenic ncRNAs (lncRNA/circRNA) or as an upstream negative transcriptional regulator of tumor-suppressive lncRNAs." (PMID 36551531, 2022).
tumor (continued). "In addition to the two aforementioned axes (lncRNA-ATB/miR-200c/ZNF217/TGF-β2 and MALAT1/miR-141-3p/ZNF217/TGF-β2), both involved in the activation of the TGF-β signaling pathway and EMT, ZNF217 is part of additional intricate ceRNA-driven regulatory circuits involved in tumor progression." (PMID 36551531, 2022). "ZNF217 overexpressing OVCA420 cells formed metastatic tumors on ovary and the peritoneal cavity whereas no tumor was observed in mice injected with control cells." (PMID 41345234, 2025).
hematologic cancers (2 papers, 2023 to 2024). "The present work investigates the chemo-preventive properties of cucurbitacin D, a compound with a broad range of anticancer effects, in hematological cancer cells, specifically with regard to its ability to modulate ZNF217 expression." (PMID 39770403, 2024). "In non-hematologic cancers, DNA binding of ZNF217 to specific cis-regulatory regions correlates negatively with gene expression, suggesting its function as a transcriptional repressor through interaction with epigenetic regulators such as CoREST, CtBP, LSD1, and EZH2." (PMID 37648814, 2023).
hematological malignancies (1 paper, 2021). "From the analysis on the “Total” data set IGF2BP1, ALKBH5, IGF2BP2, RBM15, METTL3, ZNF217 is the potentially carcinogenic gene in hematological malignancies." (PMID 33816257, 2021).
ZNF217 also shares sentences with these, for which no sentence is quoted: bone metastasis (3 papers); asthma (2); cardiovascular diseases (2); pneumonitis (2); allergic disease (1); atherosclerosis (1); B cell lymphoma (1); B-cell acute lymphoblastic leukemia (1); breast disease (1); cholangiocarcinoma (1); chronic lymphatic leukemia (1); clear cell carcinoma (1); clear-cell renal-cell carcinomas (1); colon cancer (1); colorectal tumors (1); eczema (1); endometrial cancer (1); endometriosis (1); hay fever (1); intervertebral disc degeneration (1); invasive ductal breast carcinoma (1); male breast carcinoma (1); neuroblastoma (1); non-small cell lung carcinoma (1); oesophageal adenocarcinoma (1); polycystic ovary syndrome (1); renal cell carcinoma (1); T-cell lymphoma (1); triple-negative breast carcinoma (1); type 2 diabetes mellitus (1).